AP3S2 (adaptor related protein complex 3 subunit sigma 2)
Description:
Part of the AP-3 complex, an adaptor-related complex which is not clathrin-associated. The complex is associated with the Golgi region as well as more peripheral structures. It facilitates the budding of vesicles from the Golgi membrane and may be directly involved in trafficking to lysosomes. In concert with the BLOC-1 complex, AP-3 is required to target cargos into vesicles assembled at cell bodies for delivery into neurites and nerve terminals.
Synonyms: sigma3b; AP3S3
Tractability: Antibody: UniProt places it where antibodies can reach, with medium confidence. PROTAC: ubiquitination databases record sites on it; its protein half-life has been measured.
Gene: Protein-coding gene on chromosome 15 (89,830,599 to 89,894,638, reverse strand). Ensembl gene ENSG00000157823.
Subcellular location: Golgi apparatus; Cytoplasmic vesicle membrane
Subcellular location (Human Protein Atlas): Vesicles
Gene Ontology:
Molecular function: AP-3 adaptor complex binding
Biological process: anterograde axonal transport; anterograde synaptic vesicle transport; clathrin-coated vesicle cargo loading, AP-3-mediated; melanosome assembly; platelet dense granule organization; synaptic vesicle coating; synaptic vesicle recycling; vesicle-mediated transport; Golgi to vacuole transport; intracellular protein transport; protein transport
Cellular component: AP-3 adaptor complex; early endosome; axon cytoplasm; cytoplasmic vesicle membrane; Golgi apparatus; membrane coat; synaptic vesicle
Genetic constraint (gnomAD): Loss-of-function variants: 22 observed, 24.09 expected, observed/expected ratio (o/e) 0.91, 90% interval 0.65 to 1.3. The upper end of that interval is the gene's LOEUF score, 1.3, which puts it in group 5 of 6, group 1 being the genes least tolerant of losing a copy. Missense variants: 241 observed, 246.17 expected, observed/expected ratio (o/e) 0.98, 90% interval 0.88 to 1.09. Synonymous variants: 86 observed, 90.88 expected, observed/expected ratio (o/e) 0.95, 90% interval 0.79 to 1.13.
Homologues: Orthologues: dog AP3S2 (100% identical), mouse Ap3s2 (100% identical), rat Ap3s2 (100% identical), rabbit AP3S2 (99% identical), pig AP3S2 (99% identical), guinea pig AP3S2 (98% identical), zebrafish ap3s2 (91% identical), tropical clawed frog ap3s2 (86% identical), Drosophila melanogaster or (75% identical), Caenorhabditis elegans aps-3 (73% identical). Paralogues in human: AP3S1 (84% identical), AP1S1 (31% identical), AP1S2 (30% identical), AP1S3 (29% identical), AP2S1 (28% identical), AP4S1 (27% identical).
Diseases named in the same sentence as AP3S2 in open-access papers:
AP3S2 is named in the same sentence as 12 diseases in open-access papers, as found by Europe PMC text mining. Sharing a sentence is not in itself a finding about the gene and the disease. The quoted sentences say what the papers report.
type 2 diabetes (12 papers, 2012 to 2025). "Previous study identified that some AP3S2 genetic variants are related to the onset of type-2 diabetes." (PMID 34707778, 2021). "AP3S2 gene expression is associated with carotid plaques and obesity in individuals with type 2 diabetes mellitus." (PMID 28924246, 2017). "A locus of particular relevance is AP3S2 previously reported in a GWAS of type 2 diabetes and associated in our study with cis haplotypes involving the additive effects of 3 SNPs, rs7173483, rs3803536 and rs1269077." (PMID 23382694, 2013). "The results indicated that rs2028299 near AP3S2 was significantly associated with BMI only when both patients and controls were used for the analysis, with adjustment for age, sex, and disease state of type 2 diabetes (rs2028299, β = −0.007, SE = 0.003, p = 0.0032)." (PMID 23029454, 2012). "The remaining SNPs were directionally consistent with South Asian estimates and three (AP3S2 rs2028299, GRB14 rs3923113 and HNF4α rs4812829) were nominally (p < 0.05) associated with type 2 diabetes in DIAGRAM." (PMID 25145545, 2014). "This lead SNP was annotated as 3’UTR_variant of AP3S2 gene, which may be related to type 2 diabetes mellitus (T2DM) in humans." (PMID 31931702, 2020). "The observation that DNA sequence variation and DNA methylation at this locus is associated with increased expression levels of ANPEP suggests a role for ANPEP in the pathogenesis of type 2 diabetes, rather than the gene AP3S2 proposed by prior GWAS." (PMID 26825526, 2016). "The expression of AP3S2 has been shown to be ubiquitous, and no report has yet emerged to suggest a functional role of this gene product in the pathogenesis of obesity or type 2 diabetes." (PMID 23029454, 2012).
diabetes (5 papers, 2019 to 2023). "Several diabetes risk variants increased the expression of genes in multiple tissues, including AP3S2 (rs4932265-T), CCDC92 (rs7978610-G), HLA-DQA2 (rs601945-G) and a lncRNA RP11-252K23.2 (rs3115960-G)." (PMID 35568807, 2022). "AP3S2 and GPSM1 have also associated to diabetes and other metabolic disorder by impairing the function of Golgi vesicles formation and trafficking to lysosomes and cell signaling respectively." (PMID 36037214, 2022).
Cirrhosis (1 paper, 2016). A chronic disorder of the liver in which liver tissue becomes scarred and is partially replaced by regenerative nodules and fibrotic tissue resulting in loss of liver function. "Moreover, a cirrhosis risk score consisting of SNPs in 7 genes (AP3S2, AQP2, AZIN1, DEGS1, STXBP5L, TLR4, and TRPM5) has been shown to predict fibrosis progression in HCV infected patients." (PMID 26950933, 2016).
Hypertension (1 paper, 2017). The presence of chronic increased pressure in the systemic arterial system. "Therefore, our results suggest that the linear decrease in KLF2, HPX, TMEM8A, ADAMTS-8 and AP3S2 expression in the broiler kidney is directly or indirectly related to blood pressure, hypertension and weight gain." (PMID 28924246, 2017).
rubella (1 paper, 2023). A viral infection caused by the rubella virus. "In rubella, including five in whole blood (JAGN1, RRP12, RP11-452K12.7, CASP7, and AP3S2), four in the lung tissue (IL17RC, FAM86HP, AMACR, and RRP12), and four in the transformed fibroblast cells (PPP2R1B, C11orf1, DLAT, and TMEM117)." (PMID 37020999, 2023).
AP3S2 also shares sentences with these, for which no sentence is quoted: Obesity (5 papers); Anxiety (2); COVID-19 (1); Epileptic encephalopathy (1); Hyperglycemia (1); Insulin resistance (1); metabolic disorder (1).